LRRTM1 (leucine rich repeat transmembrane neuronal 1)
Description:
Exhibits strong synaptogenic activity, restricted to excitatory presynaptic differentiation, acting at both pre- and postsynaptic level.
Synonyms: FLJ32082
Tractability: Antibody: UniProt places it where antibodies can reach, with medium confidence; UniProt predicts a signal peptide or a membrane-spanning region; its Gene Ontology location is reachable by antibodies, with medium confidence. PROTAC: its protein half-life has been measured.
Gene: Protein-coding gene on chromosome 2 (80,288,351 to 80,304,752, reverse strand). Ensembl gene ENSG00000162951.
Subcellular location: Cell membrane; Postsynaptic cell membrane
Subcellular location (Human Protein Atlas): Golgi apparatus
Pathways (Reactome):
Neuronal System: Neurexins and neuroligins
Gene Ontology:
Molecular function: signaling receptor activity
Biological process: positive regulation of synapse assembly
Cellular component: axon; cell surface; endoplasmic reticulum; GABA-ergic synapse; growth cone; postsynaptic specialization membrane; plasma membrane; postsynaptic membrane; synapse
Genetic constraint (gnomAD): Loss-of-function variants: 8 observed, 37.06 expected, observed/expected ratio (o/e) 0.22, 90% interval 0.13 to 0.39. The upper end of that interval is the gene's LOEUF score, 0.39, which puts it in group 1 of 6, group 1 being the genes least tolerant of losing a copy. Missense variants: 557 observed, 731.79 expected, observed/expected ratio (o/e) 0.76, 90% interval 0.71 to 0.82. Synonymous variants: 326 observed, 334.74 expected, observed/expected ratio (o/e) 0.97, 90% interval 0.89 to 1.07.
Homologues: Orthologues: chimpanzee LRRTM1 (99% identical), macaque LRRTM1 (99% identical), guinea pig LRRTM1 (98% identical), pig LRRTM1 (98% identical), dog LRRTM1 (98% identical), mouse Lrrtm1 (97% identical), rat LRRTM1 (97% identical), rabbit LRRTM1 (90% identical), tropical clawed frog lrrtm1 (78% identical), zebrafish lrrtm1 (65% identical). Paralogues in human: LRRTM3 (44% identical), LRRTM4 (44% identical), FLRT2 (20% identical), FLRT3 (20% identical), LRRC15 (19% identical), PODN (19% identical), NYX (18% identical), PODNL1 (18% identical), FLRT1 (18% identical), RTN4R (18% identical), RTN4RL1 (17% identical), LRRC4 (17% identical), and 10 more.
Diseases named in the same sentence as LRRTM1 in open-access papers:
LRRTM1 is named in the same sentence as 15 diseases in open-access papers, as found by Europe PMC text mining. Sharing a sentence is not in itself a finding about the gene and the disease. The quoted sentences say what the papers report.
schizophrenia (13 papers, 2010 to 2025). A major psychotic disorder characterized by abnormalities in the perception or expression of reality. "We chose this paradigm because it involves activation of neurons in the mPFC62 and the fact that impaired social interactions are a diagnostic criterion for schizophrenia, making them relevant for assessing disease-linked roles of LRRTM1." (PMID 36709330, 2023). "The LRRTM1 gene has previously been related to claustrophobia-like behavior in LRRTM1-deficient mice, and schizophrenia in humans." (PMID 36890545, 2023). "In support of this the imprinted gene LRRTM1 (Leucine-rich repeat transmembrane neuronal 1) was reported to be a risk factor for mental illness such as schizophrenia when the gene was inherited from the father." (PMID 27895608, 2016). "LRRTM1 hypomethylation in the promoter was reported as a risk factor for the development of schizophrenia." (PMID 28117656, 2016). "In light of the fact that LRRTM1 is associated with schizophrenia, we suggest that the Lrrtm1 KO mouse would be useful for further clarifying the involvement of LRRTM1 in schizophrenia." (PMID 21818371, 2011). "Recent genetic linkage analysis has shown that LRRTM1 (Leucine rich repeat transmembrane neuronal 1) is associated with schizophrenia." (PMID 21818371, 2011). "Just as the association of PCSK6 with dyslexia led to suggestion of a polygenic pathway, so the association of LRRTM1 with schizophrenia may lead to other pathways influencing handedness and brain asymmetry." (PMID 24465175, 2014). "LRRTM1, an imprinted gene that affects neuronal differentiation and connectivity, correlates with schizophrenia/schizoaffective disorder." (PMID 36056316, 2022). "The impaired cognitive function of Lrrtm1 KO mice seems to be related to the cognitive dysfunction seen in schizophrenia patients." (PMID 21818371, 2011). "We next evaluated the effect of the antipsychotic clozapine, which has been widely used in both clinical and preclinical studies of schizophrenia, on the behavioral abnormalities in Lrrtm1 KO mice." (PMID 21818371, 2011). "Because specific malfunction of the glutamate receptor is proposed to be a potential pathogenic mechanism in schizophrenia, our results suggest that the involvement of LRRTM1 dysfunction in schizophrenia needs to be considered." (PMID 21818371, 2011). "The behavioral phenotypes in Lrrtm1 KO mice thus partly resemble the signs of schizophrenia." (PMID 21818371, 2011). "No genetic locus has been clearly identified, although some evidence points to the involvement of leucine-rich repeat transmembrane neuronal 1 (LRRTM1) gene on chromosome 2p12, a maternally suppressed gene that appears to be associated paternally with handedness and schizophrenia." (PMID 20300635, 2010). "LRRTM1 (Leucine rich repeat transmembrane neuronal 1, OMIM 610867) is an emerging candidate gene for schizophrenia." (PMID 21818371, 2011). "Moreover, many cis-NAT gene pairs in mammalian brain, including the genes involved in Alzheimer's disease and LRRTM1/Ctnna2, a pair of cis-NAT genes that participates in schizophrenia, can generate nat-siRNAs." (PMID 22439910, 2012). "Although the pharmacobehavioral phenotype was not entirely characteristic of those of schizophrenia model animals, the impaired cognitive function may warrant the further study of LRRTM1 in relevance to schizophrenia." (PMID 21818371, 2011).
Anxiety (3 papers, 2011 to 2022). Intense feelings of nervousness, tension, or panic often arise in response to interpersonal stresses. "Time spent in the inner and outer zones of the open field was equivalent between the genotyopes, indicating that deletion of Lrrtm1 and Lrrtm2 in the dorsal hippocampus does not increase risk-associated anxiety behavior." (PMID 35662394, 2022). "Although panic disorder is generally considered to fall in the category of anxiety, the anxiety-like behaviors in Lrrtm1 KO mice were not clear." (PMID 21818371, 2011). "Thus, conditional deletion of Lrrtm1 and Lrrtm2 in dorsal hippocampus of adult mice does not alter avoidance-related anxiety behavior in mice." (PMID 35662394, 2022). "The region selective functions of LRRTM1 and LRRTM2 are further demonstrated by the lack of effect of Lrrtm1 and Lrrtm2 deletion in the dorsal hippocampus on social interaction or avoidance-related anxiety, which have been linked to the ventral hippocampus." (PMID 35662394, 2022). "However, the precise roles of PRKCG and LRRTM1 in TAO are unknown, and we suspected they may be involved in the mechanisms of the impaired emotional regulation and higher tendency to depression or anxiety occurring in TAO patients." (PMID 36056316, 2022). "The preference of Lrrtm1 KO mice to stay in the corners of the OF box suggested enhanced anxiety; however, the LD and EPM tests did not reveal typical traits of enhanced anxiety." (PMID 21818371, 2011).
ovarian carcinoma (1 paper, 2019). A malignant neoplasm originating from the surface ovarian epithelium. "For RFS of patients with ovarian cancer, SPOCK2 and FAXDC2 were unfavorable prognostic biomarkers but ADAMDEC1, CCNA2, FAM181A, FOXA2, LRRTM1, NEIL3 and XPR1 were favorable prognostic biomarkers." (PMID 31794425, 2019).
LRRTM1 also shares sentences with these, for which no sentence is quoted: autism (2 papers); mental illness (2); schizoaffective disorder (2); Alzheimer disease (1); autism spectrum disorder (1); dental caries (1); depression (1); male infertility (1); obsessive-compulsive disorder (1); panic disorder (1); Strabismus (1); tumor (1).